CD44 (CD44 molecule (IN blood group))
Diseases named in the same sentence as CD44 in open-access papers (continued):
Sharing a sentence is not in itself a finding about the gene and the disease.
serous ovarian cancer (12 papers, 2009 to 2024). "Our recent studies have confirmed the presence of high CD44 immunostaining particularly in the peritumoral stroma of serous ovarian carcinomas which was associated with high HA and versican expression." (PMID 21541039, 2011). "In addition, expression of CD44 spliced variant 6 (CD44v6) was reported to be associated with a shortened overall survival in stage III-IV patients as well as the recurrence of ovarian serous cancer." (PMID 31497537, 2019). "CD44-positive spheres isolated from ovarian serous adenocarcinomas by this technique have been shown to form tumors more efficiently in animal models." (PMID 25886038, 2015). "Previous studies have shown that CD44-hyaluronan interaction engages a cascade of signalling events to promote ERα activation in a serous ovarian cancer cell line." (PMID 21695196, 2011). "Our recent studies have confirmed the presence of high HA levels in the peritumoral stroma of serous ovarian carcinomas which correlate with CD44 and versican expression." (PMID 21541039, 2011). "However, the expression of other CSC markers identified in serous ovarian cancer cells including PROM1 (CD133) and CD44 were not affected by 4-MU treatment in spheroids formed by the primary serous ovarian cancer cells." (PMID 31443261, 2019).
brain cancer (11 papers, 2009 to 2025). A primary or metastatic malignant neoplasm affecting the brain. "Several studies have indicated that the upregulation of CD44 in many cancer types, including prostate, ovarian, and brain cancer, is correlated with aggressive biological behavior and poor prognosis." (PMID 39020106, 2024). "Previous studies have shown that hyaluronic acid interacts with CD44, relieving colon, breast, and brain cancer cell migrations." (PMID 34356331, 2021). "CD44 is expressed in many cancers, including lung, breast, colon, prostate, and brain cancer." (PMID 30210550, 2018). "The association between the expression level of HER-family members, EGFRvIII, CD44, and CD109, and the overall survival of Brain cancer patients." (PMID 40227788, 2025). "Some of the uniquely expressed genes include CD44 (quantified in FPW1), ERBB2 (quantified in RN1), and OLIG2 (quantified in PB1) and are genes with key roles in brain cancer." (PMID 31973233, 2020). "initially demonstrated the efficacy of a label‐free and highly sensitive techniques in detecting and quantifying elevated levels of CD44 and CD133 in exosomes derived from brain cancer cells, which were immune captured from the blood and CSF of a mouse model with brain cancer." (PMID 38020711, 2023).
gallbladder cancer (11 papers, 2016 to 2024). "Western blot results suggested that Bufalin decreased the expression of stemness-associated surface proteins CD133 and CD44, and stemness-associated factors Sox2 and Oct4, which further illustrated that Bufalin has the inhibitory effect on gallbladder cancer stem cells." (PMID 32231716, 2020). "As the levels of the mRNA of ESRP1 is down-regulated, the CD44 variant isoform is replaced by the CD44 standard isoform which promotes EMT, increasing invasiveness in gallbladder cancer." (PMID 31552163, 2019). "Besides, Bufalin inhibited the tumor sphere formation capability of gallbladder carcinoma in matrigel, reduced the expression of multiple stemness-associated proteins, including Oct4, Sox2 and the stem cell-surface marker proteins CD133 and CD44." (PMID 32231716, 2020). "The expression levels of CD68 and CD163 in M2-like TAMs and CD44 and CD133 in gallbladder cancer stem cells (GBCSCs) were increased and positively correlated in GBC tissues compared with those in neighboring noncancerous tissues." (PMID 39138521, 2024).
psoriasis (11 papers, 2016 to 2025). An autoimmune condition characterized by red, well-delineated plaques with silvery scales that are usually on the extensor surfaces and scalp. "Communication between hair follicle cells and Langerhan cells was associated with COL4A2/CD44 and LAMC1/CD44 in psoriasis, contrasting with a relatively weak HBEGF/EGFR ligand-receptor pair in normal skin." (PMID 38289616, 2024). "In all three psoriasis mouse models, neutrophil number and immunofluorescence (CD11b and CD44) and CXCL16 expression were increased to different degrees in the IMQ + PBS group as compared to the NC group." (PMID 37160878, 2023). "Studies have found that HA can improve psoriasis treatment by inhibiting CD44 and PKCa interactions to achieve anti-allergic effects." (PMID 36151726, 2022). "The HA-modified ethosomes showed specific adhesion CD44 in imiquimod-induced psoriasis-like inflamed skin, and that the increased topical drug delivery of curcumin reduced TNF-α, IL-17A, IL-17F, IL-22, and IL-1β mRNA levels; and lower CCR6 protein expression." (PMID 32848737, 2020). "Analysis of cell surface markers expression on B cells (i.e., CD40, CD44, CD80, CD86,CD11b, and HLA-DR) is the key to understand their pathogenic role in psoriasis." (PMID 27532281, 2016). "Communication between hair follicles and mast cells, melanocytes, and myeloid cells only occurred in psoriasis, focusing on COL4A2/CD44 and APP/CD74 ligand-receptor pairs." (PMID 38289616, 2024). "During psoriasis induction, TACC1 mice maintained significantly higher proportions of activated CD44+CD25+ Tregs and effector CD62L-CD44+ Tregs in skin-draining LNs." (PMID 37594540, 2023). "We believe that targeting the E-selectin-binding site on CD44/HCELL could be a viable option to treat skin diseases, such as psoriasis, for a number of reasons relating to homeostasis." (PMID 28515724, 2017). "Therefore, our results confirm that CD40, CD44, CD80, and CD86 are likelyimportant in the pathogenesis of psoriasis, especially at the active stage." (PMID 27532281, 2016). "The surface markers of DMSCs derived from both psoriasis and healthy individual were positive for CD105, CD29, CD44, CD73 and CD90 and negative for CD45, CD34 and CD14." (PMID 36065978, 2022). "Moreover, in vivo-activated T-cells isolated from psoriasis patients strongly suggest that both PSGL-1 and CD44, but not CD43, are the major E-selectin ligands." (PMID 28515724, 2017). "Additionally, we demonstrated the relevance of our findings to chronic autoimmune disease, by showing that CD44/HCELL and PSGL-1, but not CD43, from T-cells isolated from psoriasis patients, bind E-selectin." (PMID 28515724, 2017).
acute lymphoblastic leukemia (10 papers, 2013 to 2024). Leukemia with an acute onset, characterized by the presence of lymphoblasts in the bone marrow and the peripheral blood. "Previous studies have demonstrated that overexpression of CD44 in acute lymphoblastic leukemia cells enhanced drug efflux and promoted chemotherapy resistance." (PMID 32742599, 2020). "Investigations into chemotherapy drug efflux activity in human T-cell acute lymphoblastic leukemia (T-ALL) cell lines revealed a positive correlation between enhanced drug efflux activity and increased CD44 expression." (PMID 38542115, 2024). "In T-cell acute lymphoblastic leukemia (T-ALL) and other T-cell malignancies, the relevance of CD44 expression is unknown." (PMID 28163708, 2017). "Acute lymphoblastic leukemia (ALL) with mixed lineage leukemia (MLL) gene rearrangements (MLL+ALL) has a dismal prognosis and is characterized by high surface CD44 expression." (PMID 28569787, 2017).
Cirrhosis (10 papers, 2019 to 2025). A chronic disorder of the liver in which liver tissue becomes scarred and is partially replaced by regenerative nodules and fibrotic tissue resulting in loss of liver function. "In line with the increase in CD44 levels, soluble CD44 was upregulated in severe acute or chronic liver disease, including hepatitis and cirrhosis." (PMID 38790021, 2024). "According to the aim of this study, we first analyzed CD44 expression in a cohort of human patients with cirrhosis (n = 10) and in HCC patients of mixed etiology (n = 67), including HCC related to metabolic syndrome diseases (NAFLD/NASH)." (PMID 35164326, 2022). "Notably, CD44 expression tended to be higher in patients with cirrhosis, consistent with reports linking CD44 to liver fibrogenesis and chronic liver injury." (PMID 40791212, 2025). "While CD44 appears to have adaptive functions, its role in cirrhosis is complex and may vary depending on the specific context, necessitating additional investigation." (PMID 38603681, 2024). "The increased level of CD44 in CCl4-treated rats was much higher in deceased rats with cirrhosis than in surviving rats with cirrhosis, indicating that CD44 levels could be an indicator of overall survival in a cirrhotic model." (PMID 38731968, 2024). "CD44 transcript levels are significantly higher in HCC patients than in those with cirrhosis." (PMID 35164326, 2022). "The increases in each of the macrophage subtypes seen in non-tumour liver in association with NAFLD-HCC were independent of the presence or absence of cirrhosis (F8D), although the increase in CD44+ macrophages was significantly associated with the presence of T2DM (F8C)." (PMID 34408183, 2021). "This included pro-inflammatory pathways such as TNF–TNFRSF1A/B, MIF–CD74+CD44, and several MHC class II–CD4 interactions, suggesting that macrophages play an active antigen-presenting and inflammatory role during cirrhosis." (PMID 41153430, 2025). "The DINAH study is an observational one, but highlights these features as also being key in the development of NAFLD-HCC, even in the absence of cirrhosis, where T2DM associated CD44+ macrophage phenotype is acquired." (PMID 34408183, 2021).
epilepsy (10 papers, 2016 to 2025). A brain disorder characterized by episodes of abnormally increased neuronal discharge resulting in transient episodes of sensory or motor neurological dysfunction, or psychic dysfunction. "Additional studies are required to elucidate the relationship between CD44 and the Glu transporters, xCT, and EAAT2 and the association with CD44 isoforms to further understand the mechanisms underlying postoperative late epilepsy." (PMID 40002787, 2025). "In humans, transcriptome analysis in epileptic patients identified CD44 as one of the five most important proteins associated with the pathogenesis of epilepsy." (PMID 37296604, 2023). "A growing body of evidence indicates that the elevated expression of CD44 is associated with epilepsy-related brain injuries." (PMID 37296604, 2023). "So, we highlighted the functional role of CD44 as a key molecule in the occurrence of postoperative late epilepsy in GBM." (PMID 40002787, 2025). "Consistently, immunofluorescent analysis showed that CD146+ pericytes in human GBM tissues were partly stained with CD44, whereas pericytes in brain tissues from patients with epilepsy barely had CD44 staining." (PMID 41001759, 2025). "Increased dendritic spine density and decreased PSD size in CD44 AsKO animals upon seizures indicate that CD44 deletion from astrocytes can have beneficial effects on brain structure after epilepsy-related injury." (PMID 37296604, 2023). "Recently, CD44 was identified in genome-wide transcriptome analysis as one of the treatment targets for epilepsy in rats and humans." (PMID 37296604, 2023). "To shed light on the role of CD44 in the development and progression of epilepsy, we characterized the expression of CD44 in the mouse hippocampus after kainic acid-induced seizures." (PMID 37296604, 2023). "When considering that occurrence of postoperative late epilepsy is a cellular event before development of tumor recurrence in GBM, it will be very important to know how CD44 interacts with potential molecules participating in the seizure attack in postoperative late epilepsy." (PMID 40002787, 2025). "According to the univariate analysis, 13 variables were significantly associated with survival: age, performance status, extent of surgery, tumor depth, tumor size, epilepsy, postoperative chemoradiotherapy, IDH mutations, CD44, HIF-1α, HIF-1β, vimentin, and PDFGR." (PMID 38927417, 2024). "CD44 is upregulated during injury and other pathological conditions, including epilepsy." (PMID 37296604, 2023). "For example, elevated HA or CD44-mediated retention of HA may be used to suppress elevated excitatory synaptic transmission in epilepsy." (PMID 34685554, 2021). "Because of the reports of CD44 increase in epilepsy and in tuberous sclerosis, which is often accompanied by seizures, we examined a group of neurosurgical specimens removed from patients with temporal lobe epilepsy, both the hippocampi and the adjacent temporal isocortex, for CD44+ astrocytes." (PMID 38247821, 2024). "Overall, our work suggests that CD44 signaling is involved in astrocyte coverage of neuronal synapses in the ML of the hippocampus and that astrocyte morphological modifications may translate to functional changes in the pathology of epilepsy." (PMID 37296604, 2023). "In the present study, to elucidate the mechanisms underlying postoperative epileptogenesis in GBM, we focused on the expressions and functions of CD44, xCT, and EAAT2 as potential molecules closely related to late epilepsy." (PMID 40002787, 2025). "More studies should be conducted to further examine the function of CD44, TIMP1, and SERPINE1 in epilepsy." (PMID 33225612, 2020). "Although this is the most thorough study of CD44+ astrocytes in the human CNS, and we show the conversion of protoplasmic astrocytes to being CD44+ in hypoxia and epilepsy, our observations do not imply specific molecular mechanisms." (PMID 38247821, 2024).
epilepsy (continued). "On the other hand, a huge increase in the number of CD44-positive astrocytes was observed in the post-mortem brains of Alzheimer’s disease patients, which was not related to epilepsy." (PMID 37296604, 2023). "The 5 Hub genes, including C3, CD44, ANXA2, HTR1E, and APP, were also identified as the BottleNeck genes, that is, they are Hub-BottleNeck genes, indicating that they are much more important than the remaining Hub genes in the pathogenesis of epilepsy in PT." (PMID 33123575, 2020).
fibrosarcoma (10 papers, 2010 to 2024). A malignant mesenchymal fibroblastic neoplasm affecting the soft tissue and bone. "Together, this is in line with the possibility that the binding of extracellular, not surface bound, low molecular weight hyaluronan to the receptors RHAMM and CD44 induces the formation of cell adhesion, cell motility and invasion of fibrosarcoma." (PMID 36400790, 2022). "Antibodies directed against a v6-encoded epitope of CD44 or CSPG8, the co-receptor of Met, inhibited receptor activation and signaling, and abrogated tumor growth and metastasis in a fibrosarcoma model." (PMID 28548074, 2014). "In this paper we discuss the involvement of hyaluronan/RHAMM/CD44 mediated signaling in the insidious pathways of fibrosarcoma progression." (PMID 24083250, 2013). "Throughout fibrosarcoma progression, the involvement of HA, CD44 and RHAMM in signaling mechanisms significantly impacts essential cellular processes like migration, adhesion and proliferation, potentially leading to fibroblastoid cell malignant transformation." (PMID 39050866, 2024). "These conflicting observations could be explained if paediatric fibroblasts and Infantile fibrosarcoma is less dependent on the levels of CD44 than and adult fibroblasts and fibrosarcoma." (PMID 36400790, 2022). "Unraveling the complex characteristics of the hyaluronan/RHAMM/CD44 signaling axis in fibrosarcoma may reveal specific targets of pharmacological interventions." (PMID 24083250, 2013). "Interestingly, CD44 can mediate the adhesion of platelets to hyaluronan secreted by fibrosarcoma cells." (PMID 24083250, 2013). "CD44 appears to be a mediator of fibrosarcoma development and metastatic dissemination." (PMID 24083250, 2013). "Importantly, CD44 was the only adhesion-related molecule consistently expressed among the early metastatic colonies derived from tumor clones of a murine fibrosarcoma." (PMID 24083250, 2013). "The described plasticity of CD44 gene expression in fibrosarcoma during metastasis could be relevant to discrete metastasis stages." (PMID 24083250, 2013). "CD44 is not the only partner known to interact with podoplanin through the TM region, since tetraspanin CD9, which has four TM domains, was reported to bind podoplanin through TM domains 1 and 2 in fibrosarcoma cells." (PMID 33003440, 2020).
kidney cancer (10 papers, 2015 to 2025). Primary or metastatic malignant neoplasm involving the kidney. "Twist2 is known to regulate ITGA6 and CD44 expression in the ECM-receptor interaction pathway to promote kidney cancer cell proliferation and invasion." (PMID 41450820, 2025). "Unfortunately, other studies examining the role of CD44 as a prognostic marker in kidney cancer evaluated it only in the case of the ccRCC." (PMID 36831550, 2023). "In fact, the conversion of HA from HMW to LMW in context of the HAS/HA/CD44 signaling complex has been found to mediate tumor progression and thus presents a promising therapeutic target for kidney cancer research." (PMID 34009465, 2022). "Second, RCC spheres expressed the mesenchymal marker CD44, and this is consistent with the mesenchymal cell-related surface marker expression reported in the self-renewing cell population of kidney cancer and human embryonic kidney cell line." (PMID 25011053, 2015). "In addition, there is a report that CD44 expression is upregulated via ECM-receptor interaction in kidney cancer." (PMID 32545709, 2020). "A study reported that Twist2 regulates the expressions of CD44 and ITGA6 in the ECM-receptor interaction pathways, thereby stimulating the invasion and proliferation of kidney cancer cells." (PMID 35028418, 2022).
malignant glioma (10 papers, 2017 to 2025). A grade III or grade IV glioma arising from the central nervous system. "This study indicated that epileptogenicity in malignant glioma requires the co-existence and reciprocal expression of CD44 and xCT, so both could be potential targets for anti-epileptic and anti-tumoral therapies in GBM." (PMID 40002787, 2025). "In malignant glioma patients, whole transcriptome and miRNA expression profiling showed that miR-138 was negatively regulated and its expression level was negatively correlated with the expression level of CD44 molecules." (PMID 36964570, 2023). "Moreover, both stRNA-seq and scRNA-seq indicated that BRMS1 + microglia may promote the proliferation and invasion of malignant glioma cells through SPP1/CD44-mediated intercellular interactions." (PMID 39143438, 2024). "CD44 was up-expressed in malignant gliomas, notably in the 1p/19q non-codeletion cases, isocitrate dehydrogenase (IDH) wild-type, and mesenchymal subtypes in GBM samples." (PMID 36776876, 2023).